MUTYH (mutY DNA glycosylase)
Description:
Involved in oxidative DNA damage repair. Initiates repair of A*oxoG to C*G by removing the inappropriately paired adenine base from the DNA backbone. Possesses both adenine and 2-OH-A DNA glycosylase activities.
Synonyms: MYH
Tractability: Small molecule: a structure with a bound ligand is known. PROTAC: ubiquitination databases record sites on it.
Target class: Enzyme; Hydrolase
Safety:
Unwanted effects reported when the protein is acted on. In parentheses: how it was acted on, where the effect was seen, and who reports it.
grade 3-4 neutropenia (source: ClinPGx)
Gene: Protein-coding gene on chromosome 1 (45,329,163 to 45,340,893, reverse strand). Ensembl gene ENSG00000132781.
Subcellular location: Nucleus; Mitochondrion
Subcellular location (Human Protein Atlas): Nucleoplasm
Pathways (Reactome):
DNA Repair: Cleavage of the damaged purine; Displacement of DNA glycosylase by APEX1; Recognition and association of DNA glycosylase with site containing an affected purine
Disease: Defective MUTYH substrate binding; Defective MUTYH substrate processing
Gene Ontology:
Molecular function: MutLalpha complex binding; MutLbeta complex binding; MutSalpha complex binding; MutSbeta complex binding; protein binding; purine-specific mismatch base pair DNA N-glycosylase activity; 8-oxo-7,8-dihydroguanine DNA N-glycosylase activity; adenine/guanine mispair binding; DNA N-glycosylase activity; oxidized purine DNA binding; 4 iron, 4 sulfur cluster binding; catalytic activity; DNA binding; hydrolase activity, acting on glycosyl bonds
Biological process: base-excision repair; depurination; DNA repair; mismatch repair; negative regulation of necroptotic process; response to stress
Cellular component: mitochondrion; nucleoplasm; nucleus
Genetic constraint (gnomAD): Loss-of-function variants: 64 observed, 77.12 expected, observed/expected ratio (o/e) 0.83, 90% interval 0.68 to 1.02. The upper end of that interval is the gene's LOEUF score, 1.02, which puts it in group 4 of 6, group 1 being the genes least tolerant of losing a copy. Missense variants: 633 observed, 700.02 expected, observed/expected ratio (o/e) 0.9, 90% interval 0.85 to 0.97. Synonymous variants: 234 observed, 276.71 expected, observed/expected ratio (o/e) 0.85, 90% interval 0.76 to 0.94.
Gene-disease validity (ClinGen):
ClinGen rates the evidence that MUTYH causes each of these diseases.
familial adenomatous polyposis 2 (autosomal recessive): Definitive. An autosomal recessive hereditary cancer predisposition disorder caused by pathogenic variants in the MUTYH gene.
colorectal cancer (autosomal dominant): Disputed. A primary or metastatic malignant neoplasm that affects the colon or rectum.
familial ovarian cancer (autosomal dominant; autosomal recessive): Disputed. An instance of ovarian cancer that is caused by an inherited modification of the individual's genome.
hereditary breast carcinoma (autosomal recessive): Disputed. Breast carcinoma that has developed in relatives of patients with history of breast carcinoma.
hereditary breast carcinoma (autosomal dominant): Refuted.
Cancer hallmarks: tumour promoting inflammation; genome instability and mutations (suppresses); cell replicative immortality; proliferative signalling (promotes); escaping immune response to cancer; escaping programmed cell death (promotes); invasion and metastasis (promotes)
Homologues: Orthologues: chimpanzee MUTYH (99% identical), macaque MUTYH (90% identical), rabbit MUTYH (82% identical), pig MUTYH (82% identical), dog MUTYH (81% identical), guinea pig MUTYH (79% identical), mouse Mutyh (77% identical), rat Mutyh (64% identical), tropical clawed frog mutyh (51% identical), zebrafish mutyh (48% identical). Paralogues in human: NTHL1 (11% identical).
Diseases named in the same sentence as MUTYH in open-access papers:
MUTYH is named in the same sentence as 200 diseases in open-access papers, as found by Europe PMC text mining. Sharing a sentence is not in itself a finding about the gene and the disease. The quoted sentences say what the papers report.
colorectal cancer (128 papers, 2004 to 2026). "MUTYH is a DNA base excision repair gene, and its mutation can induce the development of polyposis and colorectal cancer." (PMID 42018848, 2026). "Bi-allelic germline MUTYH mutations cause a rare, Mendelian recessive syndrome of colorectal adenomas, duodenal polyps and colorectal cancer (CRC), in which tumours have excess somatic C:G > A:T mutations and the mutational signature SBS36." (PMID 42092060, 2026). "Monoallelic APC gene PVs and the biallelic inactivation of MUTYH are frequent causes of hereditary adenomatous polyposis and colorectal cancer." (PMID 40869938, 2025). "While some mutations in the MUTYH gene are associated with colorectal cancer, most MUTYH variants identified in sequencing databases are classified as variants of uncertain significance." (PMID 40156857, 2025). "A prominent example is MUTYH, a base excision repair factor associated with polyposis and colorectal cancer, which has a pathogenic variant carrier rate approaching 1 in 50 individuals in some populations." (PMID 40093110, 2025). "In a global study of colorectal cancer cases where those with Lynch syndrome or MUTYH mutation carriers were excluded, 138/6085 (2.3%) of colorectal cancer cases were found to have a metachronous colon cancer over a median follow-up of 12 years." (PMID 41170468, 2025). "The results of the present study are consistent with a recent study examining germline variants in the MUTYH gene in Latin American patients with colorectal cancer." (PMID 40869938, 2025). "Colorectal cancers (CRCs) from people with biallelic germline likely pathogenic/pathogenic variants in MUTYH or NTHL1 exhibit specific single base substitution (SBS) mutational signatures, namely combined SBS18 and SBS36 (SBS18+SBS36), and SBS30, respectively." (PMID 39793275, 2025). "For example, individuals with bi-allelic variants in MUTYH, a gene involved in oxidative DNA damage repair, are at significantly increased risk of developing colorectal cancer (log10(OR) = 4.7 [95% CI = 3.38–6.01], p = 2.2 × 10−12)." (PMID 38944039, 2024). "Genetic testing revealed a heterozygous pathogenic variant, c.1187G>A (p.G396D), in the MUTYH gene seen in MUTYH-associated polyposis and colorectal cancer." (PMID 39233942, 2024). "The threat of OG and the importance of its repairare underscored by the association between inherited dysfunctionalvariants of the MutY human homologue (MUTYH) and colorectal cancer,known as MUTYH-associated polyposis (MAP)." (PMID 38471078, 2024). "FBXW7 mutations have been associated with higher tumor mutation burden in colorectal cancer, and MUTYH mutations are associated with increased lifetime risk of colorectal cancer." (PMID 38685065, 2024). "MUTYH-associated polyposis (MAP) is an autosomal recessive disorder where the inheritance of constitutional biallelic pathogenic MUTYH variants predisposes a person to the development of adenomas and colorectal cancer (CRC)." (PMID 40225933, 2024). "The recent introduction of multigene panels in cancer genetics has led to the detection of monoallelic germinal MUTYH variants in several types of neoplasms as breast, ovarian, endometrial and colorectal cancer." (PMID 38790183, 2024). "These include MUTYH and colorectal cancer, GJB2 and hearing loss, and a pleiotropic association of FLG with both dermatitis and asthma." (PMID 38944039, 2024). "The NCBI human variant database, ClinVar, lists this variant as pathogenic/likely pathogenic arising from its association with MUTYH-associated polyposis, an autosomal recessive hereditary condition typified by the development of colorectal carcinomas." (PMID 39001544, 2024). "MAP is an autosomal recessive syndrome caused by biallelic germline mutations (either homozygous or compound heterozygous) on MUTYH that predisposes to both colonic polyposis and colorectal carcinoma." (PMID 38254803, 2024).
colorectal cancer (continued). "While biallelic germline mutations in MUTYH are associated with adenomatous polyposis and increased risk of colorectal cancer, the relative cancer risk for heterozygous carriers is less clear." (PMID 36808802, 2023). "Specifically, biallelic pathogenic germline variants in MUTYH gene have been associated with MUTYH-associated polyposis, an autosomal recessive condition which increases the risk of colorectal cancer." (PMID 37656691, 2023). "It is imperative to note that biallelic mutations in MUTYH are correlated with the onset of familial adenomatous polyposis-2 and colorectal cancer." (PMID 38003901, 2023). "Germline biallelic MUTYH mutations can result in MUTYH-associated colorectal polyposis and predisposition to colorectal cancer." (PMID 37568604, 2023). "Farrington and colleagues conducted a comprehensive study revealing that biallelic MUTYH mutations result in a 93-fold increase in the risk of colorectal cancer." (PMID 38201513, 2023). "Pathogenic germline variations in MUTYH damage its function, causing intestinal polyposis and colorectal cancer." (PMID 36979362, 2023). "PC‐D also had somatic LOH at MUTYH, resulting in biallelic inactivation of MUTYH, a constellation conferring a heritable predisposition to colorectal carcinoma and possibly other malignancies termed MUTYH‐associated polyposis." (PMID 36808802, 2023). "Among five individuals with monoallelic MUTYH variants, four exhibited polyposis with the polyp number ranging from below 20 (in three individuals) to over 100 (in one), and three had late-onset colorectal cancer." (PMID 36387175, 2022). "A large meta-analysis defined that MUTYH bi-allelic variants are associated to a 28-fold increased risk for colorectal cancer, while monoallelic variants had a limited effect." (PMID 36035419, 2022). "Carriers of germline biallelic pathogenic variants in the MUTYH gene have a high risk of colorectal cancer." (PMID 35668106, 2022). "Human MUTYH is a known tumor suppressor, and homozygous or compound heterozygous inactivating mutations in the MUTYH gene greatly increase the risk of colorectal cancer." (PMID 35806289, 2022). "The MUTYH gene variant (rs36053993) has been well described as a pathogenic variant in patients causing adenomatous polyposis and colorectal cancer through a reduction of DNA binding and glycosylase activity." (PMID 36315513, 2022). "MUTYH monoallelic variant carriers had an approximately two-fold increased risk of colorectal cancer and showed an increased risk of gastric, liver and endometrial tumors (3.34, 3.09 and 2.33, respectively)." (PMID 36077770, 2022). "Biallelic MUTYH P/LP variants are associated with an autosomal recessive disorder, characterized by polyposis and increased risk of colorectal carcinoma." (PMID 35264596, 2022). "Some studies have found an increased risk of colorectal cancer (CRC) in monoallelic carriers of MUTYH pathogenic variants, but the role of early surveillance colonoscopy is not conclusive." (PMID 34244858, 2021). "Although mutations in MutY homolog (MUTYH) are best known for MUTYH associated polyposis and colorectal cancer, it plays a role in the development of ovarian cancer." (PMID 33419231, 2021). "Monoallelic germline pathogenic mutations in MUTYH are associated with a moderately increased risk of colorectal cancer, and although their relation with breast cancer risk is controversial, some studies had reported an increased risk." (PMID 34445631, 2021). "Biallelic and monoallelic MUTYH mutations are known to be associated with increased risk of colorectal cancer (CRC) 26, 30 as well as gastric cancer, hepatobiliary cancer, endometrial cancer, and breast cancer." (PMID 34093829, 2021). "The importance of MUTYH in genome maintenance is underscored by the correlation between inheritance of functionally compromised variants and colorectal cancer, referred to as MUTYH-associated polyposis (MAP)." (PMID 34232996, 2021).
colorectal cancer (continued). "To exemplify how PWAS works, we begin with a demonstration of the analysis over a specific gene—MUTYH, a well-known predisposition gene for colorectal cancer." (PMID 32665031, 2020). "The involvement of MUTYH deficiency in the pathogenesis of colorectal cancer spurred interest in possible splice-site mutations in human malignancies." (PMID 31277343, 2019). "The majority of MUTYH splice mutations are implicated in MUTYH-associated polyposis and other types of colorectal cancer." (PMID 31277343, 2019). "Germline biallelic inactivation of MUTYH represents a familial cancer syndrome, and patients of bi-allelic MUTYH mutation carriers have an increased risk of developing colorectal cancer." (PMID 30886832, 2019). "A possibly pathogenic mutation OGG1 c.137G>A affecting the last nucleotide in exon 1 was discovered in heterozygote in a colorectal cancer patient who also carried a heterozygous I223V mutation in the coding region of MUTYH." (PMID 31277343, 2019). "The NCCN guidelines for Genetic/Familial High-Risk Assessment of Colorectal Cancer mention that there is some evidence of a slightly increased risk of CRC in MUTYH heterozygotes and therefore suggest specialized screening for CRC in some carriers." (PMID 31159747, 2019). "One patient was heterozygous for a known pathogenic variant in MUTYH, with a family history of early onset colorectal cancer consistent with the reported cancer risk for this gene." (PMID 31780696, 2019). "Mono-allelic MUTYH mutations have been reported in 1.4% of cancer-free controls, and 3.3% of colorectal cancer patients with family history." (PMID 30093976, 2018). "MUTYH-associated polyposis (MAP) and colorectal cancer (CRC) are the well-characterized hereditary conditions related to MUTYH mutations." (PMID 28173856, 2017). "Mutations in MUTYH predispose individuals to colorectal cancer, as well as increased risk of developing OC." (PMID 25889687, 2015). "A defect in phosphorylation of MUTYH was also found to cause a mutator phenotype in different microsatellite stable colorectal cancer cell lines." (PMID 23450852, 2013). "The availability of a rapid and inexpensive method for the identification of MUTYH sequence variants is relevant for the diagnosis of colorectal cancer susceptibility, since the MAP phenotype is highly variable." (PMID 21777424, 2011). "MUTYH-associated polyposis (MAP) is a recessive, hereditary, colorectal cancer-predisposing syndrome caused by biallelic mutations in the MUTYH gene." (PMID 21962078, 2011). "Biallelic MUTYH mutations have also been found to be appended with 93-fold excess risk of colorectal cancer, with practically complete penetrance by 60 years of age." (PMID 20687945, 2010). "Fourteen MUTYH variants that had previously been identified in patients with colorectal polyposis and/or colorectal cancer were selected, and their expression vectors were prepared by site-directed mutagenesis." (PMID 20848659, 2010). "Mutations in the human MUTYH gene are responsible for colorectal cancer in familial adenomatous polyposis." (PMID 20706593, 2010). "Some studies have suggested that mono-allelic changes in MUTYH increase colorectal cancer risk however this remains to be confirmed." (PMID 19338676, 2009). "Recently, genetic variants in MUTYH have been associated with a recessive form of colorectal cancer, known as MUTYH associated polyposis or MAP." (PMID 19338676, 2009). "MUTYH Associated Polyposis (MAP), a Polyposis predisposition caused by biallelic mutations in the Base Excision Repair (BER) gene MUTYH, confers a marked risk of colorectal cancer (CRC)." (PMID 19506731, 2008). "Carriers of bi-allelic MUTYH germline mutations have a risk of approximately 60% to develop colorectal carcinoma (CRC)." (PMID 17605803, 2007). "Bi-allelic MUTYH mutations are found in 10–25% of patients with between 10 and a few hundred adenomas and in 1% of patients with a colorectal carcinoma." (PMID 17605803, 2007).
colorectal cancer (continued). "The observation that germline mutations in the oxidative DNA damage repair gene MUTYH cause colorectal cancer (CRC) provides strong evidence that dysregulation of the base excision repair (BER) pathway influences disease susceptibility." (PMID 17029639, 2006). "Mutations in the MUTYH gene have been reported to be associated with increased risk of developing colorectal cancer." (PMID 16804517, 2006). "This study confirms, in a combined data set of over 7000 cases across several study populations, that the association between variants in the MUTYH gene and colorectal cancer risk is valid." (PMID 16804517, 2006). "The other person had mutations in the MUTYH gene (rs34612342) related to colorectal cancer." (PMID 40504832, 2025). "Colorectal cancer is often associated with MUTYH mutations, but their connection to breast cancer remains unclear." (PMID 38254803, 2024). "Homozygous MUTYH PVs are associated with colorectal cancer and adenomatous polyposis while homozygous PVs in MEFV cause Familial Mediterranean Fever (FMF), a relatively prevalent disease in people who live around the Mediterranean region, including the Druze population." (PMID 37107695, 2023). "Furthermore, individuals carrying monoallelic MUTYH mutations exhibit an augmented susceptibility to a spectrum of cancers, including gastric cancer, liver cancer, colorectal cancer, and endometrial cancer." (PMID 38003901, 2023). "Our findings together with published reports indicate that individuals with monoallelic MUTYH variants may be predisposed to colorectal polyposis of a variable degree and have a moderately increased risk of colorectal cancer." (PMID 36387175, 2022). "On the one hand, we found variants in known cancer genes (such as MUTYH, associated with colorectal cancer risk) that might explain a certain feature of the patient’s phenotype, but not the development of a syndrome that resembles PHTS." (PMID 35227301, 2022). "MUTYH germline mutations are best known for their role in colorectal cancer." (PMID 35428225, 2022). "Preclinical studies have revealed that mutations in MUTYH represent distinct C>A transversion and increased lymphocytic infiltration in colorectal cancer, suggesting that tumors with MUTYH mutations may efficiently respond to ICIs." (PMID 34026622, 2021). "Somatic MUTYH mutations have been described in sporadic colorectal cancer and may occur concurrent to somatic adenomatous polyposis coli (APC) gene mutations." (PMID 33419231, 2021). "In addition, 16 patients were heterozygous for pathogenic variants in genes known to have a recessive pattern of inheritance, i.e., the colorectal cancer (CRC) predisposition genes MUTYH and NTHL1." (PMID 31263571, 2019). "A large meta-analysis of genetic variants associated with colorectal cancer derived an aggregate relative risk of 1.17 (95% CI 1.01–1.34) for monoallelic mutations in MUTYH, less than the relative risk of having a first-degree relative with colorectal cancer (RR 2.25, 95% CI 2.00-2.53)." (PMID 30093976, 2018). "MUTYH mutations are associated with colorectal cancer (CRC)." (PMID 26109431, 2015). "Κnockout mice for both enzymes are strongly prone to lung, ovarian cancers and lymphomas, and have shortened life spans, whereas human germline biallelic MUTYH mutations have been implicated in MUTYH-associated polyposis, a condition associated with increased risk of colorectal cancer." (PMID 24705290, 2014). "The prevalence of MAP is estimated to be around 1% of all colorectal cancer cases and MUTYH mutations have been found in 7%, and 10% of FAP patients and 40% of AFAP patients, respectively." (PMID 23450852, 2013). "MUTYH-associated polyposis (MAP) (MIM#608456), a recessive inherited syndrome characterized by colorectal adenomatous polyposis and a high risk of colorectal cancer, is a disorder caused by biallelic pathogenic germline variants in the human mutY homologue (MUTYH) gene." (PMID 21962078, 2011).